RAD51B (RAD51 paralog B)
Diseases named in the same sentence as RAD51B in open-access papers (continued):
Sharing a sentence is not in itself a finding about the gene and the disease.
tumor (continued). "Interestingly, evDNA detected five additional variants (BRAF L319I, RAD51B T107K) in patients 3, 4, 9 and 10 that were not present in the respective tumor." (PMID 35205822, 2022). "RAD51 paralogs, including RAD51B, RAD51C, RAD51D, XRCC2 and XRCC3, have emerged as essential tumour suppressors, forming two subcomplexes, BCDX2 and CX3." (PMID 39268578, 2024). "Upon review of the RAD51 paralogs, both RAD51B (7th percentile) and RAD51D (6th percentile) showed low RNA expression in the tumor compared to the TCGA STAD dataset." (PMID 36964191, 2023). "The impact of alterations in RAD51B, GID4, and POT1 on telomeric content was proportional to tumor purity, but in samples WT for known TMM genes, telomeric content was not impacted by tumor purity." (PMID 37709802, 2023). "Focally deleted regions identified the tumour-suppressor genes RHOA at 3p21, CDKN2A and CDKN2B at 9p21, RAD51B, MAX, DICER1, BCL11B, NKX2-1, CCNB1IP1 and BAZ1A at 9q33." (PMID 34980126, 2022). "Individually, RAD51B displayed over 80% sensitivity and specificity, whereas XRCC3 correctly identified 43.4% of the tumor samples with 94.7% specificity." (PMID 32295201, 2020). "Five HR cofactors – the RAD51 paralogs RAD51B, RAD51C, RAD51D, XRCC2 and XRCC3 – recently emerged as crucial tumor suppressors." (PMID 32669601, 2020). "The results showed that in many cases, chemoresistant tumours inactivated tumour suppressor genes (RB1, NF1, RAD51 paralog B (RAD51B), PTEN) through gene breakage." (PMID 31146417, 2019). "Furthermore, RAD51B and XRCC3 promoter levels were higher in tumor tissues compared to normal breast or lymph node, although with statistical significance for XRCC3, only." (PMID 32295201, 2020). "Three patients had germline variants of uncertain significance (ACMG Class 3) in FANCG, RAD51B, and RPA1, respectively, whose allele frequencies were not increased in the tumor compared with the normal control sample." (PMID 30967556, 2019). "Furthermore, Rad51b deletion induces the recruitment of the PRC2 complex to the ERα promoter region, which catalyzes the trimethylation of histone H3 at lysine 27, resulting in decreased ERα expression during tumor progression." (PMID 41318657, 2025). "Furthermore, XRCC3 promoter methylation levels were lower in normal adjacent tissue comparing to tumor tissue (p = 0.002), whereas RAD51B promoter methylation levels were higher in tumor samples, although not reaching statistical significance (p = 0.968)." (PMID 32295201, 2020).
movement disorder (1 paper, 2017). Neurological conditions resulting in abnormal voluntary or involuntary movement, which may impact the speed, fluency, quality and ease of movement. "Variants in the paralog RAD51, whose protein product interacts with that of RAD51B, have been associated with congenital mirror movement disorders (OMIM 614508) and mirror movement phenotypes are also associated with PD23." (PMID 28117402, 2017).
RAD51B also shares sentences with these, for which no sentence is quoted: adenocarcinoma (3 papers); anemia (2); lung squamous cell carcinoma (2); nasopharyngeal carcinoma (2); angiosarcoma (1); B-cell lymphoma (1); benign mesenchymal tumors (1); benign tumours (1); brain cancer (1); colon adenocarcinoma (1); cutaneous melanoma (1); endometrial cancer (1); endometrial stromal tumor (1); female reproductive diseases (1); fibrosarcoma (1); glioblastoma (1); head and neck cancer (1); hereditary cancer (1); hereditary cancer syndromes (1); hypothyroidism (1); inflammatory myofibroblastic tumor (1); Li-Fraumeni syndrome (1); lymph node metastasis (1); Lynch syndrome (1); metabolic syndrome (1); metastatic disease (1); metastatic prostate carcinoma (1); myeloma (1); non-alcoholic fatty liver (1); pancreatic adenocarcinoma (1).
A further 14 diseases each share a sentence with RAD51B in 1 paper.